FZD3 (frizzled class receptor 3)
Diseases named in the same sentence as FZD3 in open-access papers (continued):
Sharing a sentence is not in itself a finding about the gene and the disease.
colorectal adenoma (3 papers, 2008 to 2021). An adenoma that arises from the colon or rectum. "The significance of it is not known yet and therefore it will be interesting to examine the expression of FZD3 protein in a large cohort of primary and metastatic CRC samples and colorectal adenoma (CAD) samples." (PMID 24255701, 2013). "Since the qualitative review of expression indicated induction of NKD1, FZD3 and FZD6 in colorectal adenomas, we developed quantitative real-time RT–PCR assays for each of these to determine the extent of the induction." (PMID 18414471, 2008). "In this paper, we show that NKD1, FZD3 and FZD6 transcripts are all induced significantly in colorectal adenomas compared to matched normal tissue, indicating that both the Wnt/PCP and the Wnt/Ca2+-response pathways are expressed at an early stage in tumour formation." (PMID 18414471, 2008).
esophageal squamous cell carcinoma (3 papers, 2013 to 2025). Esophageal squamous cell carcinoma (ESCC) is a type of esophageal carcinoma (EC) that can affect any part of the esophagus, but is usually located in the upper or middle third. "Conversely, hsa‐miR‐30a‐5p has been shown to enhance 5‐FU sensitivity in esophageal squamous cell carcinoma by downregulating Frizzled Class Receptor 3 (FZD3), a transmembrane receptor involved in the Wnt signaling pathway." (PMID 40444136, 2025). "Moreover, FZD3 protein has a predominant role in Wnt-induced neurite outgrowth in Ewing sarcoma tumor cells and it is highly expressed in poorly differentiated squamous cell esophageal carcinoma tissues." (PMID 24255701, 2013). "Recent studies have shown that circRNAs derived from the Plasmacytoma Variant Translocation 1 (PVT1) gene (circPVT1) regulate 5-fluorouracil (5-FU) chemosensitivity in esophageal squamous cell carcinoma (ESCC) by modulating the Wnt/β-catenin pathway through the miR-30a-5p/FZD3 axis." (PMID 40649179, 2025).
glioma (3 papers, 2016 to 2024). A benign or malignant brain and spinal cord tumor that arises from glial cells (astrocytes, oligodendrocytes, ependymal cells). "In addition, the mRNA levels of targets were determined in miR-139-overexpressing glioma cells, which showed that miR-139 inhibited FZD3 and β-catenin expression." (PMID 34512162, 2021). "The Kaplan-Meier survival analysis of glioma patients from the TCGA and CGGA databases indicated that lower expression of FZD3 and β-catenin predicted better prognosis." (PMID 34512162, 2021). "The results indicated that OCP-PDE2A reduced cAMP concentration in gliomas and that OCP-miR-139 decreased the expression of FZD3 and β-catenin." (PMID 34512162, 2021). "Among Wnt ligands, receptors and co-receptors, we found that FZD3, ROR2, and Wnt5a regulate FZD6 overexpression-induced phenotypes in glioma spheres." (PMID 27698350, 2016).
leukemia (3 papers, 2008 to 2021). A malignant (clonal) hematologic disorder, involving hematopoietic stem cells and characterized by the presence of primitive or atypical myeloid or lymphoid cells in the bone marrow and the blood. "Fzd3 expression has been observed in the adult skeletal muscle, kidney, pancreas, cerebellum, and cerebral cortex tissues, and it is associated with esophageal carcinoma, lung squamous cell carcinoma, leukemia, myeloma, lymphoma, and Ewing sarcoma." (PMID 34671643, 2021). "However, microRNAs associated with Fzd3 have only been identified in leukemias thus far." (PMID 34671643, 2021).
neuropathy (3 papers, 2021 to 2022). A disorder affecting the nervous system that manifests with pain, tingling, numbness, and/or muscle weakness. "Older age, hyperglycemia, and obesity or poor nutritional status, such as single-nucleotide polymorphisms (SNPs) in the FGD4, EPHA5, and FZD3 genes and ABCB1 and GSTP1 polymorphisms, have been associated with the development of taxane-related neuropathy." (PMID 33922821, 2021). "Risk factors for the development of chemotherapy-induced neuropathy include older age, prior exposure to neurotoxins, diabetes, folate/B12 deficiencies, inter-individual variations in CYP2C8*3, class IIa β-tubulin, FDG4, FZD3, EPHA5, and the WNT pathway, among others." (PMID 34944858, 2021). "Regarding rs7001034 in the FZD3 gene and rs242557 in the MAPT gene, an association with neurotoxicity was observed, in particular allele A increased the occurrence of ineuropathy, although it was not confirmed for severe neuropathy." (PMID 36307826, 2022).
osteosarcoma (3 papers, 2022). A usually aggressive malignant bone-forming mesenchymal neoplasm, predominantly affecting adolescents and young adults. "Additionally, SNHG10 upregulates frizzled class receptor 3 (FZD3) to maintain the activation of the Wnt/β-catenin signaling pathway in osteosarcoma." (PMID 35149697, 2022). "Downregulated VAV3 could inhibit the angiogenesis of osteosarcoma, and inhibited FZD3 can also block the invasion and malignant growth of osteosarcoma cells." (PMID 35340229, 2022). "FZD3 can activate the EMT of osteosarcoma cells by promoting β-catenin transfer into the nucleus." (PMID 36429098, 2022). "Thus, this study suggests that the hub nodes LEF1, RUNX2, CSF1R, VAV3, FZD3, CDKN1A, and FBN1 are key factors in the progression of osteosarcoma." (PMID 35340229, 2022).
adenoma (2 papers, 2008 to 2010). A neoplasm arising from the epithelium. "In cultured cells, stabilisation of β-catenin using lithium treatment led to NKD1 expression but failed to influence Wnt/Ca2+ receptors, while Wnt growth factor treatment induced FZD3 transcripts to the degree seen in adenomas." (PMID 18414471, 2008). "While some Frizzleds (FZDs) were downregulated in adenomas, the Wnt/Ca2+ receptors FZD3 and FZD6 were induced by a median factor of 6.5 and 4.6, respectively." (PMID 18414471, 2008). "The most striking change found, however, was that for the Wnt/Ca2+ receptor FZD3, which was expressed in 13 of 19 adenomas, but only in 2 of 13 normal tissues (P=0.005)." (PMID 18414471, 2008). "The inter-quartile ranges of FZD3 induction in the sporadic and FAP adenoma groups (3–17 vs 1.0–26) showed much greater similarity than a similar comparison for NKD1 (79–1053 vs 2–62)." (PMID 20628379, 2010). "In addition, there was no clear relationship between NKD1 and FZD3 induction, contrasting with the expression profiles seen in adenomas." (PMID 18414471, 2008).
colorectal polyp (2 papers, 2013 to 2021). "ICC staining showed that FZD3 protein was expressed in 100% (186/186) of CRC specimens, 89% (70/79) of CAD specimens, 75% (100/133) of colorectal polyp specimens and 69% (129/186) of normal colorectal epithelial tissues adjacent to CRC tissues." (PMID 24255701, 2013). "ICC staining for FZD3 was observed in 100% (40/40) of CRC, 93% (37/40) of CAD, 70% (28/40) of colorectal polyp." (PMID 24255701, 2013). "Despite the fact that FZD3 protein was expressed in 100% of CRC specimens, 89% of CAD specimens, 75% of colorectal polyp specimens and 69% adjacent normal colorectal epithelial tissues, the immunoreactivity of FZD3 had significant difference among those 4 groups of specimens." (PMID 24255701, 2013).
colorectal tumor (2 papers, 2013 to 2023). "Therefore, FZD3 may provide an indication of the degree of Wnt ligand signaling in the colorectal tumor." (PMID 24255701, 2013). "In contrast, miR-98-5p inhibits the activity of FZD3 by binding directly to the 3′UTR of its mRNA, therefore exerting a suppressor effect on colorectal tumors." (PMID 37466730, 2023).
esophageal cancer (2 papers, 2021 to 2023). A primary or metastatic malignant neoplasm involving the esophagus. "CircPVT1 sponge miR-30a-5p targets and binds frizzled class receptor 3 (FZD3), affects the expression levels of p-β-catenin, GPX4 and SLC7A11, inhibits cellular ferroptosis, affects esophageal cancer 5-FU chemotherapy sensitivity and promotes the development of esophageal cancer." (PMID 37152286, 2023).
gastric cancer (2 papers, 2018 to 2024). A primary or metastatic malignant neoplasm involving the stomach. "Emerging evidence has demonstrated that Wnt/β‐catenin is activated after gastric cancer and plays a critical role in promoting invasion and migration through overexpressing or increasing the functions of several components of the Wnt pathway such as Wnt1, Wnt2, Wnt3, Wnt5a, Fzd‐3, CTNNB1 and LRP6." (PMID 28994231, 2018). "With the exceptions of FZD3 and FZD6, which are expressed at low levels in gastric cancer, all FZD isoforms are highly expressed in gastric cancer cells." (PMID 38952556, 2024).
metastatic carcinoma (2 papers, 2013 to 2018). A carcinoma which has spread from the original site of growth to another anatomic site. "In addition, the expression of FZD3 protein in other types of metastatic cancers was also examined in order to explore whether FZD3 protein can be used as an adjunct diagnostic marker for metastatic CRC." (PMID 24255701, 2013). "Our results are very interesting because ICC staining for FZD3 was positive to various extents in all metastatic carcinomas." (PMID 24255701, 2013). "We continued to investigate the potential of FZD3 protein as an adjunct diagnostic marker in metastatic CRC by performing ICC staining in various types of non-CRC metastatic carcinomas." (PMID 24255701, 2013).
non-melanoma skin carcinoma (2 papers, 2012 to 2017). "Wnt-pathway receptor FZD3 is strongly expressed in colorectal and non-melanoma skin cancer and during chronic lymphocytic leukemia, CLL." (PMID 28146432, 2017). "Expression of Wnt5a, Fzd3, and Fzd5 in non-melanoma skin cancer." (PMID 22384081, 2012).
oral squamous cell carcinoma (2 papers, 2022 to 2025). "The two AXIN2 mutations (c.2347G>T and c.1102G>A) were previously addressed as being associated with small cell lung and prostate cancers, respectively, while the FZD3 mutation (c.674dupT) was previously reported in oral squamous cell carcinoma (OSCC)." (PMID 35723313, 2022).
ovarian carcinoma (2 papers, 2013 to 2019). A malignant neoplasm originating from the surface ovarian epithelium. "For example, up-regulation of RASSF5 expression can inhibit the growth of OC cells, over-expression of FZD3 can increase the survival time of OC patients, and inhibition of MMP9 gene expression can block metastasis of ovarian cancer cells." (PMID 31182053, 2019).
polycystic ovary syndrome (2 papers, 2024 to 2025). A disorder that manifests as multiple cysts on the ovaries. "Additionally, FZD3 expression was significantly up-regulated in the cumulus cells from polycystic ovary syndrome patients, which damage the estrogen synthesis of cumulus cells." (PMID 39796015, 2024).
psychosis (2 papers, 2008 to 2013). "Therefore, in order to examine the roles of Fzd3 in mechanisms underlying the development of psychosis, we analyzed the FZD3 gene in patients with methamphetamine psychosis." (PMID 18702828, 2008).
acute lymphoblastic leukemia (1 paper, 2022). Leukemia with an acute onset, characterized by the presence of lymphoblasts in the bone marrow and the peripheral blood. "FZD7 and FZD8 are expressed in most acute lymphoblastic leukemia (ALL) cells, while FZD3, FZD4, and FZD9 are occasionally detected." (PMID 36452482, 2022).
acute myeloid leukemia (1 paper, 2021). Acute myeloid leukemia (AML) is a group of neoplasms arising from precursor cells committed to the myeloid cell-line differentiation. "miR-155 and miR-192 inhibit Fzd3/Wnt/β-catenin signaling in acute myeloid leukemia (AML) and decrease transformation, proliferation, and differentiation of AML progenitor cells." (PMID 34671643, 2021).
basal cell carcinoma (1 paper, 2023). A carcinoma involving the basal cells. "The regulatory network also showed that DEGs including LEF1, FZD3, SMAD3, and BMP4 were important regulators of the Wnt signaling, basal cell carcinoma, and Hippo signaling pathways." (PMID 36979137, 2023).
bone sarcoma (1 paper, 2015). A sarcoma that arises from the bone. "We found that FZD3, FZD5, FZD9 and FZD10 were prominently expressed in all bone sarcoma cells as compared to hMSC." (PMID 25999350, 2015).
Charcot-Marie-Tooth hereditary neuropathy (1 paper, 2023). "Substantial genetic evidence supports FZD3 as a causal gene for Charcot-Marie-Tooth hereditary neuropathy." (PMID 37344884, 2023).
idiopathic pulmonary fibrosis (1 paper, 2011). Idiopathic pulmonary fibrosis (IPF) is a nonneoplastic pulmonary disease that is characterized by the formation of scar tissue within the lungs in the absence of any known cause. "Konigshoff and colleagues confirmed the up-regulation of WNT1, WNT7B and WNT10B, FZD2, FZD3, β-catenin, and LEF1 expression in the lungs of individuals with idiopathic pulmonary fibrosis compared to transplant donor lung." (PMID 21490961, 2011).
liver disease (1 paper, 2008). "Of interest was the progressive accumulation of the FZD activating events (WNT3/4/5A and FZD3/6/7 upregulations and sFRP1/5 repression) with severity of the liver disease and the tumour stage." (PMID 18577996, 2008). "We have identified eight potential FZD activating events, each occurring in a significant proportion of HCCs (⩾20%) – that is, upregulation of FZD3/6/7 and WNT3/4/5A, and repression of sFRP1/sFRP5 – which accumulate with severity of the liver disease and tumour stage." (PMID 18577996, 2008).
myelodysplastic syndrome (1 paper, 2021). A clonal hematopoietic disorder characterized by dysplasia and ineffective hematopoiesis in one or more of the hematopoietic cell lines. "In a myelodysplastic syndrome (MDS) cell line, SFRP1 is transcriptionally inactivated due to epigenetic modification, allowing increased WNT ligand binding to FZD3." (PMID 34604862, 2021).
nasal polyps (1 paper, 2023). "The expression levels of DVL1, DVL3 and FZD3 mRNAs were significantly lower in the nasal polyps than in the turbinates, while those of FZD6, PRICKLE1, PRICKLE2, VANGL1 and VANGL2 mRNAs were not statistically different between the two tissues." (PMID 38232516, 2023).
non-small cell lung carcinoma (1 paper, 2022). A group of at least three distinct histological types of lung cancer, including non-small cell squamous cell carcinoma, adenocarcinoma, and large cell carcinoma. "Then the relative gene and protein expressions of let-7f and its target genes, including HMGA2, ARID3B, SMARCAD1, and FZD3, were measured in lung tissues of Non-Small Cell Lung Cancer (NSCLC) patients and A549 cell line using quantitative real-time PCR and Western blotting." (PMID 35488374, 2022).
osteoporosis (1 paper, 2024). A condition of reduced bone mass, with decreased cortical thickness and a decrease in the number and size of the trabeculae of cancellous bone (but normal chemical composition), resulting in increased fracture incidence. "FZD3 is a gene that encodes frizzled class receptor 3 (FZD3), which is a receptor in the WNT signaling pathway, an important pathway in the development of osteoporosis and part of signaling pathways regulating pluripotency of stem cells." (PMID 39086902, 2024).
psoriasis (1 paper, 2009). An autoimmune condition characterized by red, well-delineated plaques with silvery scales that are usually on the extensor surfaces and scalp. "We next characterized the expression of Wnt5a, Fzd3, Fzd5, Fzd6 in psoriasis lesions which are characterized by hyperproliferation and dysregulated differentiation." (PMID 19399181, 2009). "We included Fzd3 and Fzd5 in this analysis, since these have been reported to bind Wnt5a, as well as Fzd6, as it was found upregulated in psoriasis and squamous cell carcinoma." (PMID 19399181, 2009).
renal cell carcinoma (1 paper, 2021). "However, a recent report suggested that FZD3 was downregulated in renal cell carcinoma and downregulation of FZD3 abolished the inhibitory effect of miR-340 knockdown on cell proliferation, migration, and invasion." (PMID 34966683, 2021).
substance-induced psychosis (1 paper, 2008). "Our present and previous findings indicate that genetic variants of the FZD3 gene affect susceptibility to two analogous but distinct dopamine-related psychoses, endogenous and substance-induced psychosis." (PMID 18702828, 2008).
cancer (29 papers, 2008 to 2025). A tumor composed of atypical neoplastic, often pleomorphic cells that invade other tissues. "Furthermore, the aberrant expression of frizzled 3 receptor (FZD3) is typically associated with the development and metastasis of malignant tumors." (PMID 40265011, 2025). "In addition, String pathway interaction analysis identified six proteins (TGFBR2, TGFA, FGF21, SMAD4, TGFBR1, and FZD3) that were at the intersection of the cancer-associated pathways and, importantly, which were restored to their younger crosstalks by the rounds of TPE." (PMID 35999337, 2022). "The targeting of the FZD3 protein in breast cancer cells by 5’-tiRNA-Val inhibits the Wnt/β-catenin signaling pathway, which in turn promotes cancer cell apoptosis and slows cancer progression." (PMID 40265011, 2025). "The ncRNAs (such as lncRNA and miRNA) can directly or indirectly target fzd3, regulate the Wnt signaling pathway, and affect the proliferation and metastasis of cancer cells." (PMID 39452097, 2024). "A number of studies have shown that FZD3 is up-regulated in tissues from lung squamous cell carcinomas, lymphomas, Ewing sarcomas, and myeloma, among other cancers." (PMID 37466730, 2023). "Another study confirmed that 5′-tiRNA-Val targeted the Frizzled-3 (FZD3) protein, attenuating the Wnt/β-catenin pathway, and finally promoting the apoptosis of cancer cells." (PMID 35574338, 2022). "It has been reported that FZD3 was upregulated in some cancers and promoted the proliferation and invasion of cancer cells via the Wnt/β-catenin pathway." (PMID 34966683, 2021). "Several reports suggested that FZD3 was ungulated in cancers and promoted the proliferation and invasion of cancer cells via the Wnt/β-catenin pathway." (PMID 34966683, 2021). "Our data analysis also showed that miR-98 and miR-205 have two common predicted target genes FZD3 and RPS6KA3, which are actually genes associated with carcinoma according to the Online Mendelian Inheritance in Man (OMIM) database." (PMID 25521201, 2014). "The pattern of FZD3 induction was also markedly different in cancers, with only 40% (9 out of 23) showing significant induction, 30% (7 out of 23) essentially unchanged and the remaining 30% (7 out of 23) downregulated." (PMID 18414471, 2008). "FZD6 and FZD3 are the most highly expressed Wnt receptors in the cancer cell lines." (PMID 41286306, 2025). "The Wnt receptor Frizzled3 (FZD3) is important for brain axonal development and cancer progression." (PMID 39174501, 2024). "Furthermore, miRNAs were investigated to inhibit cancer cell proliferation and metastasis by targeting a key gene—frizzled receptor 3 (FZD3) in the Wnt signaling pathway." (PMID 37466730, 2023). "Moreover, LEF1, RUNX2, CSF1R, VAV3, and FZD3 have been reported to take part in the development of cancer." (PMID 35340229, 2022). "Overexpression or activation of FZD3 in several cancer types contributes to EMT and could be a target for chemoprevention strategies." (PMID 34604862, 2021). "FZD3 is a receptor poorly studied among FZD family in human cancers." (PMID 29789460, 2018). "There is currently no explicit method or antibody that could be taken to target FZD3 for cancer therapy." (PMID 29789460, 2018). "Those novel results can show that FZD3 protein may be involved in the metastatic process of those carcinomas." (PMID 24255701, 2013). "In summary, FZD3 ICC staining may be helpful to exclude those 2 carcinomas upon pathological diagnosis because the staining was focal and very weak in those FZD3 staining positive HCC and RCCC cases when compared to those in other tumor types." (PMID 24255701, 2013). "The data collectively show that by sponging miR-140-3p, miR-382-5p and miR-579-3p, circZNF800 promotes ALK7, FZD3 and WNT5A expression, possibly contributing to cancer stem cell properties of CRC cells." (PMID 37950151, 2023).